INS (insulin)
Diseases named in the same sentence as INS in open-access papers (continued):
Sharing a sentence is not in itself a finding about the gene and the disease.
diabetes (continued). "Leptin, insulin, and percentage of diabetes were similarly lowest in Ghanaians (26.5 ± 21.0 μg/L, 100.1 ± 44.3 pmol/L, and 1 %, respectively) and highest in the US (41.4 ± 19.2 μg/L, 170.0 ± 83.2 pmol/L, and 13 %, respectively)." (PMID 26374293, 2015). "The MRI had provided a diabetes clinic since the 1920s following the Canadian discovery of insulin therapy which had transformed diabetes from an acute and terminal illness to a chronic condition." (PMID 27499557, 2015). "Any defect in insulin production leads to improper regulation of glucose in the blood and results in diabetes." (PMID 26273663, 2015). "Diabetes mellitus is an endocrine disorder resulting from inadequate insulin release or insulin insensitivity." (PMID 26491434, 2015). "Recommendations and guidance for drivers with insulin-treated diabetes and their medical attendants have been developed, but such advice is absent in many parts of the world, where driving regulations are either very limited or non-existent." (PMID 28702227, 2015). "In early stages of diabetes, pancreatic β-cells produce excess amount of insulin, resulting in hyperinsulinemia." (PMID 25961014, 2015). "Toxicity and cell destroys block insulin production and secretion, and finally permanent diabetes occurs." (PMID 27275196, 2015). "A high level of adiponectin increases insulin sensitivity, while a low adiponectin level contributes to insulin resistance in obesity and type 2 diabetes mellitus." (PMID 26699936, 2015). "More recent research in novel treatments for AD has found promising results using medication originally developed to treat diabetes, such as insulin and glucagon-like peptide-1 (GLP-1) analogs." (PMID 26340637, 2015). "In the present case study, the patient was administered insulin to control diabetes mellitus, and used a digestive enzyme to improve malabsorption following TP." (PMID 25435983, 2015). "Thiazolidinedione (TZD), a specific synthetic ligand activator of PPAR-γ, improves glucose tolerance, insulin sensitivity, and lipid metabolism in type 2 diabetes mellitus and obesity." (PMID 26474757, 2015). "Age, height, weight, previous use of insulin therapy and diabetes duration were similar in both the groups." (PMID 25874191, 2015). "Similar studies indicate that Aloe vera extract is effective in increasing insulin sensitivity, reducing fasting blood glucose, and decreasing the level of HbA1C in patients with pre-diabetes during eight weeks." (PMID 25883909, 2015). "This study investigated factors influencing the efficacy of sitagliptin when used concomitantly with insulin to treat type 2 diabetes mellitus (T2DM) in the real-world setting." (PMID 26124906, 2015). "According to Frankieetal .9, insulin exerts ananti-inflammatory effect by acting on the glycemic control of patients with type 2diabetes mellitus." (PMID 26734798, 2015). "Patients who are prescribed insulin, perceive hypoglycemic episodes and have better diabetes knowledge are the ones who become persistent users of a PWP." (PMID 26086272, 2015). "Prevalence of diabetes mellitus before surgery was 13.5%; among them, 5% were on medication with oral agents and 2.7% with insulin." (PMID 25885408, 2015). "After the adjustment for insulin sensitivity, the declining tendency in the insulin secretory function (described by DI and DI30) became more significant with the increasing family history risk category of diabetes." (PMID 25664814, 2015). "Even a subpopulation of insulin-treated diabetes patients, those on one daily injection were excluded from this care programme as well as from the reimbursement of the necessary blood glucose monitoring material." (PMID 26171143, 2015). "It is well known that appropriate supplementation of vitamin D, especially vitamin D2, can increase insulin sensitivity, lower blood glucose, and reduce the cardiovascular complications of diabetes." (PMID 26664454, 2015).
diabetes (continued). "In the early 1990s the Ministry of Health produced a National Diabetes Plan, which proposed an equation to calculate the amount of insulin needed per year in Brazil for universal coverage and amplified public purchase of the drug." (PMID 26259708, 2015). "Larger studies are required to further investigate the utility of similar approaches in improving insulin response in diabetes." (PMID 25811109, 2015). "In the review, diabetes is characterized by insulin resistance, hyperinsulinemia and impaired insulin signaling." (PMID 26136647, 2015). "In a population of millions of individuals, this change in insulin sensitivity would translate to decreased prediabetes and diabetes mellitus in the community." (PMID 25683266, 2015). "lactis 420 improves insulin sensitivity and glucose tolerance while decreasing fat mass in dietary mouse models of diabetes and obesity." (PMID 26366205, 2015). "In particular, given the increasing incidence of diabetes, there is increasing concern of GH's effects on insulin sensitivity." (PMID 26425883, 2015). "Because insulin and EGF stimulate TRPM6 function, patients with diabetes mellitus type 2 or users of EGFR inhibitors are at risk to develop hypomagnesemia." (PMID 25774985, 2015). "Among women with diabetes, 4 were treated with insulin, 2 were diet-controlled and 3 received oral medications." (PMID 26035307, 2015). "The major predictors of greater glycemic excursion – greater age, duration of diabetes, glycated hemoglobin and, especially, the use of insulin – suggest that the main determinant of the post meal blood glucose excursion was a relative insulin deficiency." (PMID 25855488, 2015). "Confounders included age, sex, current smoking habits, leisure-time physical activity, depressive symptoms, diabetes duration, BMI, HbA1c, insulin use, HDL cholesterol, systolic blood pressure and renin-angiotensin system inhibitors use." (PMID 26599441, 2015). "The increased risk of death for diabetic patients seems to be explained mainly by patients with insulin-treated diabetes." (PMID 25880202, 2015). "Increasingly, CSII is being used as the first-line therapy at diabetes onset in preschool children; the use of insulin analogs has become standard in CSII." (PMID 25802842, 2015). "Vanadium compounds are known as promising drugs for lowering blood glucose in diabetes, due their insulin-mimetic properties and ability to counteract insulin resistance." (PMID 26053397, 2015). "The series of experiments leading to cloning and expression of insulin in the cultures cells in the 1970s was a tremendous revolution in the field of medicine and application of gene therapy in the treatment of diabetes was suggested as a possible cure." (PMID 26273667, 2015). "Treatment of diabetes need constant monitoring of blood glucose level, regulating it through modified dietary sugar intake, physical exercise and insulin therapy (subcutaneous administration) to attain normoglycemia." (PMID 26498972, 2015). "This study included 123 insulin-treated diabetic patients who were referred to the diabetes clinic between January and July 2013 at Shiga University of Medical Science Hospital." (PMID 26102197, 2015). "It is evident from the findings of the present systematic review, that Zinc plays an important role in β-cell function, insulin action, glucose homeostasis and the pathogenesis of diabetes and its complications." (PMID 26381880, 2015). "In our study, the four subjects who required insulin therapy for correction of hyperglycemia were all diabetics." (PMID 26681940, 2015). "The cells known as diabetes induced pluripotent stem cells; (DiPS) are pluripotent and have the ability to differentiate into insulin producing cells." (PMID 26273667, 2015). "In contrast, although glucose control was improved with insulin in mice with diabetes while on the HFD, once the insulin was discontinued, glucose control worsened and β-cell functions (HOMA-B %) continued to deteriorate." (PMID 25633992, 2015).
diabetes (continued). "The GA/HbA1c ratio was significantly correlated with insulin secretory beta-cell function and increased as duration of diabetes increased." (PMID 26484352, 2015). "Insulin use often leads to increased body weight, and it is always used in a later stage of diabetes, when hyperglycemia cannot be adequately controlled by oral antidiabetic agents." (PMID 26171401, 2015). "Inherited variations have been identified from studies of monogenic diabetes and have provided insights into β-cell physiology, insulin release, and action of insulin in fat, muscle, and liver." (PMID 26079428, 2015). "This study proposes a comprehensive assessment of an MTH intervention for people with insulin-requiring diabetes." (PMID 25803226, 2015). "Patients exposed to fibrates were slightly, but significantly, younger than patients exposed to statins, with a shorter history of diabetes, and they received fewer antidiabetic drugs, including insulin." (PMID 26398765, 2015). "Reduced insulin secretion and increased hepatic glucose production lead to hyperglycemia in fasting diabetes." (PMID 26273663, 2015). "The term diabetes mellitus indicates a group of metabolic disorders characterized by high blood sugar and impaired insulin signaling." (PMID 26074958, 2015). "We examined the cross-sectional relationships of coffee intake with newly diagnosed diabetes and measures of glucose homeostasis, insulin sensitivity, and insulin secretion, in a large Brazilian cohort of middle-aged and elderly individuals." (PMID 25978631, 2015). "It is beyond the scope of this review to describe the regulations for drivers with insulin-treated diabetes in every country or continent, and in many parts of the world no such driving regulations exist." (PMID 28702227, 2015). "Twenty one percent of the cohort of patients with diabetes were treated with diet, 52.8 % with oral drugs and 26.2 % with insulin; 1,703 people (0.05 %) where considered as type 1 diabetes, while 32,089 people (99.5 %) as type 2 diabetes." (PMID 26714744, 2015). "In order to identify prognostic factors for complete diabetes remission, we compared the two groups prior to surgery by considering age, diabetes duration, beta-cell function, and insulin use." (PMID 25954762, 2015). "Currently, the treatment of diabetes is focused on the change of life-long lifestyle, pharmaceutical intervention, and insulin supplementation, but less than 40% of patients have cured the disease." (PMID 26688810, 2015). "Decision coaching with children and their parents considering insulin options was feasible implement and evaluate in our diabetes clinic and was acceptable to participants." (PMID 25889602, 2015). "A fundamental goal in the management of patients with diabetes is the maintenance of normoglycaemia, often through the use of insulin." (PMID 25421366, 2015). "Although the results for the effect of maternal diabetes were unstable, previous studies observed decreased serum sex hormone binding globulin (SHBG) levels and increased insulin levels in umbilical cord blood in pregnant women with diabetes." (PMID 25798927, 2015). "More women than men were treated with insulin in keeping with their longer duration of diabetes and higher HbA1c levels." (PMID 25873955, 2015). "Guidance on the classification of the two types of diabetes from major health organisations is limited, and focuses on aetiology, whereas it is insulin production that is the driver for informing treatment decisions." (PMID 26525723, 2015). "Regarding the later finding, it seems that with the use of insulin a more complete treatment is provided among patients with uncontrolled diabetes." (PMID 26230991, 2015). "Counting carbohydrates is useful for people with insulin-requiring diabetes to administer appropriate prandial insulin doses to maintain euglycemia." (PMID 28702234, 2015).
diabetes (continued). "Values decreased during period 1 for both insulin types, indicating reductions in diabetes-specific emotional distress (−5.1 ± 11.4 for sequence A with insulin glargine, −4.4 ± 14.8 for sequence B with NPH insulin." (PMID 26055391, 2015). "The aim of this study was to investigate the efficacy of insulin degludec used for basal-bolus insulin regimen after switching from twice-daily basal insulin in Japanese patients with type 1 diabetes mellitus." (PMID 26435713, 2015). "The underlying cause of diabetes is either decrease in the synthesis/secretion of insulin (type 1 diabetes mellitus (T1DM)) or by insulin resistance, followed later by death of pancreas’ β-cells (T2DM)." (PMID 26003803, 2015). "Current guidelines for the treatment of diabetes are specific to type 1 and type 2 diabetes (T1D and T2D) and these show marked differences, reflecting the difference in endogenous insulin production between the two subtypes." (PMID 26525723, 2015). "This positive impact on glycaemic control is likely to be multifactorial, potentially reflecting the benefits of a more intensive insulin regimen, and of improved diabetes self-care/self-determination." (PMID 27274982, 2015). "Amylin is secreted along with insulin by pancreatic beta-cells and levels are low in patients with diabetes." (PMID 28702221, 2015). "CTA-oriented PCI patients had less hypertension, diabetes on insulin, dyslipidemia, and hemodialysis." (PMID 26231033, 2015). "Unexpectedly, we also observed that provision of insulin by way of allogeneic islet implantation in combination with mATG leads to a pronounced reversal of diabetes as well as restoration of tolerance to self-islets." (PMID 26580221, 2015). "While these conditions have different etiologies, both types of diabetes are characterized by hyperglycemia resulting either from insufficient insulin levels as in T1D, or by an insensitivity of target cells to insulin as in T2D." (PMID 26300887, 2015). "For example, in states such as diabetes, inadequate insulin signaling is interpreted by tissues as a state of “starvation” despite the availability of excess nutrients." (PMID 25815008, 2015). "Long-acting insulin plays a major function in the management of diabetes due to its role in basal blood glucose control." (PMID 26120575, 2015). "Diabetes was defined as either fasting glucose ≥126 mg/dL or use of oral hypoglycemic agents or insulin." (PMID 26239554, 2015). "Access to diabetes care in developing countries is described as being problematic with most of the factors documented relating to access to medicines and especially insulin." (PMID 26427953, 2015). "Defective cognitive function is common in patients with diabetes, suggesting that insulin normally exerts anabolic actions in neuron, namely, diabetic encephalopathy." (PMID 26089889, 2015). "Smokers often exhibit impairments in insulin-mediated glucose handling and an increased incidence of type 2 diabetes mellitus (T2DM)." (PMID 26075006, 2015). "Animal studies have shown that low magnesium diet can lead to impaired insulin secretion and action and magnesium supplementation decrease the incidence of diabetes." (PMID 26402695, 2015). "Intensive insulin management and good glycaemic control are essential for the prevention of acute and long-term diabetes complications and the overall wellbeing in people with type 1 diabetes." (PMID 26202844, 2015). "PPAR-γ agonists of the thiazolidinediones (TZDs) class, like rosiglitazone, are currently used to treat type-2 diabetes mellitus patients, mainly due to their insulin-sensitizing effects." (PMID 25972766, 2015). "A total of 117 diabetes patients treated with insulin completed a questionnaire including the 3L and the 5L." (PMID 25890017, 2015). "Among the diabetic group, 44 individuals (83%) were using an oral antidiabetic and 9 (17%) were using insulin; the mean duration of diabetes was 7.81±5.77 years (range, 1-20 years)." (PMID 27800231, 2015).
diabetes (continued). "Of particular interest is the increased burden of CNVs in certain KEGG pathways relevant to population health in Qatar and in the region, such as diabetes, insulin signaling and metabolism." (PMID 26490036, 2015). "Intensive insulin treatment is known to improve β-cell function in the majority of patients with newly diagnosed type 2 diabetes mellitus (T2DM), and family history (FH) is known to be an important independent risk factor for T2DM." (PMID 25574243, 2015). "Larger randomized, controlled studies are needed to definitively assess the effectiveness of diabetes education programs focusing on insulin self-adjustment for patients with T2DM." (PMID 25904987, 2015). "Hypoglycemia-associated autonomic failure, characterized by ineffective glucose counterregulation during hypoglycemia, is well described in children and adults on insulin therapy for diabetes mellitus." (PMID 26343738, 2015). "Diabetes mellitus is a group of metabolic diseases characterised by chronic excess of blood glucose (hyperglycaemia), as a result of defects in insulin secretion, insulin action, or both." (PMID 25970163, 2015). "Diabetes treatment requires specialized multi-professional teams, supplies for blood glucose monitoring and training for self-injections of human insulin or insulin analogues." (PMID 26288660, 2015). "In turn, in animal models of obesity, surgical removal of visceral fat led to an increase in insulin sensitivity and amelioration of diet-induced diabetes." (PMID 26516848, 2015). "Many patients with diabetes need to adjust long-acting therapy with a series of tailored insulin doses taken throughout each day before meals and snacks, or to correct high blood sugar levels." (PMID 25943590, 2015). "The first member of IGF family to be identified was insulin, with subsequent investigation resulting in the elucidation of its role in glucose metabolism and its implication in the aetiology of diabetes mellitus." (PMID 25866791, 2015). "It is worth noting that, other precipitating factors are the omission of insulin and undiagnosed diabetes." (PMID 26966489, 2015). "OLETF rats exhibit hyperphagia, obesity, insulin resistance, and impaired insulin secretion: most of the male rats are diagnosed with diabetes by oral glucose tolerance test (OGTT) at 25 weeks of age." (PMID 26366137, 2015). "Guidance that promotes safe driving practice has been provided for drivers with insulin-treated diabetes, which is the group principally addressed in this review." (PMID 28702227, 2015). "Transgenic mice overexpressing miR-7 in β cells developed diabetes due to impaired insulin secretion and β cell dedifferentiation." (PMID 26211738, 2015). "Type 2 diabetes mellitus (T2DM) is characterized by a resistance to insulin action and inadequate compensatory insulin secretory response, leading to hyperglycemia." (PMID 26697121, 2015). "In vivo, DGLHD significantly inhibited insulitis, delayed the onset and development of diabetes, promoted insulin secretion and sensitivity, and balanced partially normalized Th1 and Th2 cytokines in NOD mice." (PMID 26358493, 2015). "The Global Diabetes Advocate and Vietnamese partner stated that a strength of the RAPIA was that it provided “a formalized approach” to documenting the situation with regards to diabetes care and access to insulin in low- and middle-income countries." (PMID 26427953, 2015). "The association of self-reported diabetes with DHF was stronger in diabetic patients being treated, especially if treated with insulin or more than 1 drug (aOR 3.36; 95% CI 0.72–15.61)." (PMID 25909658, 2015). "The increased risk of death of diabetic patients with HF seems to be mainly explained by patients with insulin-treated diabetes." (PMID 25880202, 2015). "Most of the diabetes patients (97 %) were on intensive insulin treatment using insulin pumps or >4 insulin injections a day." (PMID 26408307, 2015).